INS (insulin)
Diseases named in the same sentence as INS in open-access papers (continued):
Sharing a sentence is not in itself a finding about the gene and the disease.
Insulin resistance (continued). "Indeed, a cohort study found a significant association between a dietary GI-related measure (i.e., the insulin load) and pancreatic cancer risk in people with pre-existing insulin resistance but not in insulin-sensitive subjects." (PMID 39125388, 2024). "Given that skeletal muscle mRNA expression of myostatin was increased and insulin sensitivity was impaired in participants with excess adiposity in our in vivo study, we next sought to examine whether the induction of insulin resistance can directly affect myostatin expression." (PMID 37801203, 2024). "Insulin sensitivity was evaluated using the homeostasis model assessment of insulin resistance and it was observed that shrimp oil was responsible for improvements in insulin resistance and also leptin resistance, providing shrimp the ability to prevent and treat T2DM." (PMID 39728129, 2024). "However, the gene expression of AKT2, SREBF1, and GLUT4, and lipogenic genes regulated by insulin was significantly lower in the INS_K group, indicating that some cows have more severe insulin resistance that cannot be relieved by exogenous insulin supplementation." (PMID 39881718, 2024). "According to the homeostasis model assessment of insulin resistance, UA levels are linearly correlated with fasting insulin levels, and a linear increase in UA levels correlates with a linear increase in insulin resistance measured using the homeostasis model assessment of insulin resistance." (PMID 38753584, 2024). "As a result, the release of SFA from the gut microbiota decreases serum NEFA levels induced by insulin resistance and may help improve blood glucose responses through competition in insulin-sensitive tissues, e.g., adipose and muscle, leading to increased glucose uptake." (PMID 37242267, 2023). "However, insulin resistance may occur when normal or increased insulin levels produce a reduced biological response, usually when there is reduced insulin sensitivity." (PMID 36831374, 2023). "Although these compounds can alter glucose homeostasis via inflammation-mediated insulin resistance, urea can directly induce β-cell dysfunction: elevated levels of urea increase islet protein O-GlcNAcylation and impair glycolysis, resulting in insulin secretory defects." (PMID 37525273, 2023). "Moreover, in mammals it is proved that TNFα induces insulin-resistance, by impairing insulin-stimulated glucose uptake through the inhibition of insulin signaling at the insulin receptor substrate level, but on the other hand, TNFα increases basal glucose uptake in adipose tissue." (PMID 36998471, 2023). "In clinical practice the interpretation of laboratory and anthropometric parameters could predict the level of insulin, highlighting also a possible underlying diagnosis of insulin resistance and/or hyperinsulinemia without performing an OGTT." (PMID 37754306, 2023). "From a physiological perspective, sleep deprivation has been shown to promote insulin resistance in both healthy subjects and those with type 1 diabetes, and both lower sleep efficiency and quality also seem to play a role by decreasing insulin sensitivity and increasing glucose variability." (PMID 40303250, 2023). "Meanwhile, increased insulin-stimulated SOD1 expression suggests increased O2• − dismutation capacity, which may integrate with the PRX2 and GPx1 responses and counteract the chronic oxidative stress associated with insulin resistance." (PMID 37812879, 2023). "However, if a pregnant woman requires high doses of insulin because of severe insulin resistance, metformin may be added in order to reduce the daily insulin requirement." (PMID 37765126, 2023). "In addition, FYGL could balance fatty acid biosynthesis and metabolism to effectively dissipate energy, therefore reducing insulin resistance and increasing insulin sensitivity in vivo." (PMID 37553709, 2023).
Insulin resistance (continued). "Thus, global phosphoproteomics studies suggest that understudied branches of insulin signalling may be major mediators of insulin resistance." (PMID 37248992, 2023). "Indeed, many studies have shown a favorable effects of KD on insulin resistance in subjects with overweight or obesity; however, some studies observed, intriguingly, a significant improvement in insulin sensitivity in response to low carbohydrate diets even in the absence of weight loss." (PMID 37513538, 2023). "Interestingly, a previous work showed that muscle cells were directly responsible for insulin resistance caused by viral infections instead of VAT, which reinforces the hypothesis of homeostatic role of insulin resistance." (PMID 37026009, 2023). "Alternatively, it could be speculated that attenuated synthesis of proteins involved in canonical insulin signalling and mitochondrial biogenesis have a more significant role in the induction of disuse-mediated insulin resistance over a longer duration of time." (PMID 37153211, 2023). "Therefore, the development of leptin resistance in skeletal muscle, characteristic of obesity, may lead to insulin resistance in that tissue by allowing the accumulation of intramuscular lipids and disruption of the insulin signaling pathway." (PMID 36998471, 2023). "Although alcohol-fed Tlr4fl/fl mice developed systemic insulin resistance, Tlr4LKO mice were insulin sensitive after excessive alcohol drinking as evidenced by lower normalized blood glucose levels after 30 min of insulin injection, which was comparable to mice pair-fed control liquid diet." (PMID 36979389, 2023). "Increased circulating NEFA concentrations are involved in insulin resistance (by negatively impacting the insulin secretory capacity of the pancreas), and therefore a decrease in circulating NEFA due to dietary betaine supplementation may be beneficial to heat-stressed ruminants." (PMID 37238121, 2023). "The altered balance between myo-Ins and D-Chiro-Ins, resulting in a relative excess of the latter component, may represent a causative, relevant factor dramatically fostered by insulin secretion, even in the absence of an overt condition of insulin resistance." (PMID 37047265, 2023). "Interestingly, MBOAT7 is downregulated by acute injection of insulin in both liver and adipose tissue, suggesting the possibility that hyperinsulinemia might worsen systemic insulin resistance through downregulation of MBOAT7." (PMID 37127068, 2023). "Antipsychotics could impact brain insulin signal and induce peripheral insulin resistance." (PMID 36676092, 2023). "Therefore, the excessive production of ROS induced by hyperglycemia, in addition to diluting the body’s antioxidant response, can also trigger a vicious cycle including hyperglycemia, oxidative stress, metabolic damage, and reduced insulin secretion or insulin resistance." (PMID 37664859, 2023). "The increasing level of INS in the prepartum blood of dairy cows may represent reduced sensitivity to insulin receptors in various organs and tissues in the body, thereby reducing insulin sensitivity and triggering insulin resistance." (PMID 36776875, 2023). "With regard to the positive correlation between PRFT and PFF, as well as fasting insulin, our results agreed with those of previous studies that PRFT was independently associated with higher insulin resistance, and fatty pancreas was correlated with insulin resistance and β-cell dysfunction." (PMID 36949492, 2023). "The mechanisms underlying the development of insulin resistance are not clear and may manifest at various levels of insulin signalling." (PMID 36860368, 2023). "Overall, data show a strong link between Gal3 and obesity-induced insulin resistance in insulin-targeted hepatocytes, adipocytes, and myocytes, and thus the specific inhibition of Gal3 may offer a potential therapeutic strategy for restoring insulin sensitivity." (PMID 37175823, 2023).
Insulin resistance (continued). "Thus, at some point, brain insulin resistance could be accompanied by reduced insulin levels at the CNS and this brain insulin deficiency has also been associated with AD onset and progression." (PMID 36901787, 2023). "Additionally, adiponectin has been found to improve insulin sensitivity and reduce insulin resistance, which may help prevent obesity and type two diabetes, known risk factors for many cancers." (PMID 37238961, 2023). "Genes on the chromosome region 11p15.5 (40.3% of R2) and others involved in insulin production (35.7% of R2) had the greatest effect in males diagnosed early, which contrasts with the major influence of genes involved in peripheral insulin resistance in females diagnosed early (52.3% of R2)." (PMID 37291636, 2023). "In addition, preptin levels are affected by fasting insulin and insulin resistance." (PMID 37434133, 2023). "In contrast, hepatic insulin resistance primarily manifests as an increase in fasting glucose levels (and in the ascending limb of the postprandial glucose excursion curve), due to the inability of insulin to switch off liver glucose output from both glycogenolysis and gluconeogenesis." (PMID 37402955, 2023). "Additionally, GS patients may experience increased insulin resistance due to elevated aldosterone levels, which dose-dependently affects the insulin signaling pathway." (PMID 38333726, 2023). "Additionally, it inhibits insulin signaling, resulting in insulin resistance and T2DM." (PMID 37762143, 2023). "Such improvements in insulin sensitivity in metabolically active organs may improve systemic insulin resistance, which may change the insulin resistance milieu in adipose tissue in patients with type 2 diabetes, such as via an increase in adiponectin and a decrease in inflammatory cytokines." (PMID 37237539, 2023). "In addition, high testosterone levels in post-menopausal women aged 55–89 years have been used to predict insulin resistance and the future incidence of type 2 diabetes, i.e., bioavailable testosterone was positively related to fasting and post-challenge glucose and insulin levels." (PMID 38068890, 2023). "This study demonstrated that supplementing mouse diets with F. prausnitzii for 5 weeks could significantly decrease the levels of plasma glucose and insulin, improving the glucose intolerance and insulin resistance (IR) index compared to T2D mice-obesity-induced diabetic animals with IR." (PMID 37025162, 2023). "Is tempting to speculate that BM-MNC have a direct action on insulin production and/or effects, however the most plausible interpretation is that BM-MNCs reduce the inflammation in the peripheral-damaged tissue and subsequently decrease insulin resistance, than a lower dose of insulin is needed." (PMID 38139339, 2023). "Given our finding that the post-TRF group sustained a partial effect on circulating monocytes and adipose tissue inflammation, we wished to learn whether the post-TRF group conveys protection against fasting blood glucose (FBG), fasting insulin (FI), and insulin resistance index HOMA-IR." (PMID 37299580, 2023). "In conclusion, besides HOMA-IR, insulin-free surrogates of insulin resistance, in particular LAP and the TyG index, could serve as useful methods to identify KTRs at risk of PTDM development, thus obviating the necessity to measure insulin." (PMID 38068348, 2023). "Another MAM protein associated with insulin resistance, PINK, has been found to be deficient, significantly increasing albumin permeability and hindering glucose uptake in podocytes, which supports the crucial role of PINK1 in maintaining insulin signal transduction and podocyte permeability." (PMID 37781026, 2023). "It was shown that the difference in insulin sensitivity in children with obesity between the sexes is due to phenotypic characteristics, that there may be a gene responsible for it, and that girls have higher insulin resistance." (PMID 36765298, 2023).
Insulin resistance (continued). "However, insulin resistance may reduce the effectiveness of insulin in activating PP2A in AD, leading to increased Tau phosphorylation." (PMID 37511207, 2023). "Furthermore, BBR stimulated insulin secretion and improved insulin resistance through different pathways, including up-regulation of protein expression of proliferator-activated receptor (PPAR)-γ, glucose transporter (GLUT) 4, PI3K/AKT, and AMP-activated protein kinase (AMPK) activation." (PMID 38275993, 2023). "This indicates that IRS1/2 is the cause of selective insulin resistance; in some cases, the insulin signal transduction in the liver remains intact, but the involuntary cellular pathway may be blocked resulting in an increase in HGP during insulin resistance." (PMID 36982617, 2023). "In addition to impaired glucose transport, insulin resistance suppresses the stimulatory effect of insulin on nitric oxide production from endothelial nitric oxide (NO) synthase because of deficient posttranslational modification of the enzyme via PI3K/AKT activity." (PMID 37854186, 2023). "Also, thiazolidinediones decrease insulin resistance and can be used in combination with insulin." (PMID 37528628, 2023). "One of the studies reported that serum insulin levels (p = 0.020) and Quantitative Insulin Sensitivity Check Index (p = 0.003) improved significantly after 6 weeks of treatment, while Homeostatic Model Assessment for Insulin Resistance (p = 0.067) improved marginally." (PMID 37569074, 2023). "Also, it has been reported that higher intakes of nitrate/nitrite from vegetables may contribute to improving cardiometabolic conditions via beneficial impact on insulin signaling pathway, insulin resistance, and inflammation and oxidative stress." (PMID 36627671, 2023). "Thus, a low SHBG level may indicate an advanced degree of existing insulin resistance, while androgen excess might reflect impaired post‐prandial insulin secretion." (PMID 36484476, 2023). "A study based on insulin resistance reported that CaMKII phosphorylates and blocks nuclear translocation of hepatocyte HDAC4 under conditions of obesity: lower nuclear HDAC4 decreases the SUMOylation and degradation of the co-repressor DACH1, and finally, causes defective insulin signaling." (PMID 37766305, 2023). "In another study performed in the HepG2 hepatoma cell line, hexanoic acid promoted basal and insulin-induced phosphorylation of the Akt-mTOR axis, maintaining a balance of lipid metabolism and potentially constituting an effective tool to manage liver steatosis and hepatic insulin resistance." (PMID 38027127, 2023). "In addition, it has been shown that PCAs reduce blood glucose levels in a dose-dependent manner favoring the expression and externalization of GLUT4 on the cell surface and improve insulin resistance by directly activating IR and other targets of the insulin signaling pathway." (PMID 37298181, 2023). "Based on in vitro studies, some researchers have hypothesized that excessive levels of triglyceride-rich VLDL particles could impair insulin action by preventing insulin from attaching to its receptor; i.e., insulin resistance might be a secondary symptom of primary dyslipidaemia." (PMID 37274075, 2023). "Given the role of RAGE activation in the development of insulin resistance, it is conceivable that silencing the signals transmitted by this receptor may represent a therapeutic strategy to improve insulin sensitivity in patients with impaired glucose tolerance." (PMID 37446161, 2023). "Chronic hyperglycemia due to a lack of insulin production or insulin resistance is associated with long-term damage, dysfunction and the failure of different organs and is a severe risk factor for various pathologies, such as cardiovascular, neurological and kidney diseases, among others." (PMID 38137918, 2023). "Thus, recent evidence suggests that ADA might have a role in insulin signaling and could serve as a marker for insulin resistance in T2DM39." (PMID 38092892, 2023).
Insulin resistance (continued). "Since I1R and I3R do not share similar ligand‐binding sites and I3R is a regulator of insulin secretion, the potential interaction of rilmenidine with the I3type imidazoline receptor might explain its effects on improved insulin resistance and, thus, glucose levels." (PMID 36670049, 2023). "However, it remains unknown if insulin modifies EVs in association with central hemodynamics, and whether body fat, adipose insulin resistance (Adipose‐IR) and/or adipokines uniquely relate to the effect of insulin on EVs." (PMID 36597186, 2023). "Thus, in hypogonadism showing insulin-sensitivity (IS), over time, insulin levels may increase, leading to insulin resistance (IR) and type 2 diabetes." (PMID 37367840, 2023). "In addition to HOMA-IR, insulin-free surrogates of insulin resistance might serve as useful methods to identify KTRs at risk of PTDM, thus obviating the necessity to measure insulin." (PMID 38068348, 2023). "To determine whether this association is more a function of increased BMI or of insulin resistance, we further divided the obese group according to their HOMA-IR values, into insulin-sensitive and insulin-resistant groups, and tested all the genetic models of rs3200401." (PMID 37104004, 2023). "In support of this, research in murine models indicate that inhibition of reactive lipid synthesis protects against high-fat diet-induced insulin resistance, while pharmacological and genetic inhibition of mitochondrial ROS emission preserves insulin sensitivity." (PMID 37153211, 2023). "Impaired insulin sensitivity may interrupt the glucose metabolism and result in excess glucose conversion to triacylglycerol in the liver, which also leads to hepatic insulin resistance." (PMID 36909338, 2023). "Moreover, it has also been demonstrated that activation of A1Rs may increase insulin sensitivity, overexpression of A1Rs could protect from insulin resistance in mice, whereas impaired glucose tolerance and insulin sensitivity was detected in A1R KO mice." (PMID 36750771, 2023). "However, high iron storage in the liver may induce insulin resistance by impairing insulin signal transduction and attenuating the liver’s ability to extract insulin." (PMID 37077360, 2023). "In addition, we reported that MO programs insulin, glucose, and lipid signaling in the liver of young adult offspring in a sex-dependent manner, leading to liver dysfunction and insulin resistance and that the male and female offspring of obese mothers have different aging metabolic trajectories." (PMID 37242132, 2023). "Additionally, when p50α/p55α knockout mice are treated with the hypothalamic toxin gold thioglucose (GTG), which typically induces hyperphagia, obesity, and insulin resistance, they demonstrate decreased insulin levels and epididymal fat, compared to GTG-treated wild-type control mice." (PMID 38317714, 2023). "These comprehensive and consistent results may suggest that the existence of appropriate Momordica charantia saponins in high-starch diets for common carp would adjust the insulin signaling pathway to remit insulin resistance through activating or restraining certain miRs." (PMID 37091861, 2023). "Thus, early and significant weight gain following intensive insulin therapy may lead to insulin resistance and may have an impact on the occurrence of remission." (PMID 37572062, 2023). "In addition, arginine can regulate glucolipid metabolism in diabetic rats, increase insulin sensitivity, improve insulin resistance, reduce plasma lipid levels and increase the body’s antioxidant capacity to reduce the metabolic diseases caused by type 2 diabetes." (PMID 37600949, 2023). "Moreover, chronic hyperglycemia contributes to hyperinsulinemia and insulin resistance; this activates the insulin growth factor signaling the pathway, which is the most adopted mechanism that accounts for the relationship between hyperglycemia and elevated cancer risk." (PMID 37568291, 2023).